CYP2C19 (cytochrome P450 family 2 subfamily C member 19)
Diseases named in the same sentence as CYP2C19 in open-access papers (continued):
Sharing a sentence is not in itself a finding about the gene and the disease.
eosinophilic esophagitis (2 papers, 2022 to 2023). Eosinophilic esophagitis (EoE) is a chronic, allergic disease of the esophagus characterized clinically by symptoms of esophageal dysfunction (including vomiting, dysphagia, feeding disorders, food impaction and abdominal pain) which persist after treatment with proton pump inhibitors (PPIs). "In children who received a dose of PPI between 1.54 and 2.05 mg/kg/day (the estimated dose to reach 80 mg per day), a binary logistic regression model showed that the presence of the CYP2C19 *17 allele was associated with a higher risk of PPI-insensitive eosinophilic esophagitis." (PMID 36143168, 2022). "In addition, rapid CYP2C19 metabolizers are associated with treatment failure in eosinophilic esophagitis." (PMID 36143168, 2022).
esophageal squamous cell carcinoma (2 papers, 2015 to 2024). Esophageal squamous cell carcinoma (ESCC) is a type of esophageal carcinoma (EC) that can affect any part of the esophagus, but is usually located in the upper or middle third. "Also, a matched case-control study in a Chinese Han population reported that the polymorphism of CYP2C19*2 has an important role in the development of esophageal squamous cell carcinoma, modified by drinking tea and consuming pickled vegetables or hot beverages/food." (PMID 39859964, 2024). "The purpose of this study was to explore the effects of CYP2C19 gene polymorphisms and various environmental factors and their interactions on the risk of esophageal squamous cell carcinoma (ESCC) in a Chinese Han population." (PMID 25927305, 2015).
fatty liver disease (2 papers, 2022 to 2023). A reversible condition wherein large vacuoles of triglyceride fat accumulate in liver cells via the process of steatosis. "In elderly female patients, a decline in CYP2C19 metabolic activity was associated with fatty liver disease presence." (PMID 37371728, 2023).
fibrosis (2 papers, 2016 to 2023). the formation of excess fibrous connective tissue in an organ or tissue in a reparative or reactive process. "From this analysis, the following factors explain 39% of the variability in CYP2C19 mRNA abundance: fibrosis stage, age, metformin use, and ALT." (PMID 36927865, 2023).
gastric ulcer (2 papers, 2022 to 2023). An ulcerated lesion in the mucosal surface of the stomach. "For example, common gastric ulcer patients used proton pump inhibitors such as omeprazole or H2 receptor inhibitor cimetidine, which are inhibitors of CYP2C19 and CYP2C9, respectively." (PMID 37790811, 2023). "Specifically, proton pump inhibitors (PPIs), which are widely used for treating H. pylori infections and gastric ulcers, are mainly metabolized in the liver by CYP2C19, thereby affecting drug efficacy." (PMID 35336597, 2022).
hemorrhagic stroke (2 papers, 2016 to 2021). A stroke caused by a bleed on the brain. "Because of the relatively small sample size, we are not sure whether these CYP2C19 gene polymorphisms are associated with hemorrhagic stroke." (PMID 27137706, 2016).
heroin addiction (2 papers, 2020 to 2021). "Our study identified variations in five candidate genes, including GRIN3A, GRIN3B, CYP2C19, TPH2, and COMT, contributing to susceptibility to heroin addiction." (PMID 33915886, 2021).
hiatal hernia (2 papers, 2016 to 2024). "Conventional PD or SSPPD with Roux-en Y reconstruction rather than PpPD should be selected to reduce the risk of DGE and prevent bile reflux, in performing PD for patients with hiatal hernia or rapid metabolizer CYP2C19 genotype; otherwise, fundoplication such as Nissen and Toupet should be added." (PMID 27090811, 2016). "This study did not gather information on hiatal hernias, H. pylori status or CYP2C19 genotype that may influence the effect of PPI treatment." (PMID 38753973, 2024).
hyponatraemia (2 papers, 2019 to 2023). "Further, the study results suggest that CYP2C19 SSRI substrates are associated with gastrointestinal absorption ADRs: diarrhoea, hyponatraemia, and again small for dates baby as well as pain-related ADRs: chest pain, pain in extremity, and pain." (PMID 31616600, 2019). "CBD inhibited CYP2C19 increasing STR exposure, producing hyponatremia and subsequent cognitive dysfunction." (PMID 37144214, 2023).
malaria (2 papers, 2014). Malaria is a serious and sometimes fatal disease caused by a parasite that commonly infects a certain type of mosquito which feeds on humans. "The magnitude of the REHH for CYP2C19*2 in Yoruba is similar to that observed for G6PD-202A (glucose-6-phosphate dehydrogenase deficiency) which is thought to confer a 50% reduction in risk of malaria." (PMID 24690327, 2014).
mood disorder (2 papers, 2023). A cognitive disorder a disturbance in which the person's mood is hypothesized to be the main underlying feature. "Genotyping for CYP2D6 and CYP2C19 variants in the context of specialized mood disorder services that offer tailored interventions to complex patients is suggested here as an additional supportive approach to complement available innovative technologies." (PMID 37490261, 2023). "The haplotype integrated by CYP2C19 alleles, and the CYP2C19 metabolizer status which was categorized as IM or PM might contribute to the risk of developing mood disorder." (PMID 36698099, 2023). "Our hypothesis is that the A allele of CYP2C19-rs4986893, as a variant, encodes impaired CYP2C19 enzyme, promoting steroid hormone disequilibrium, and resulting in a change in hypothalamic-pituitary-adrenal axis activity and mood disorder development." (PMID 36698099, 2023).
psychosis (2 papers, 2024). "In summary, the optimization of CYP2D6 and CYP2C19 genotyping is relevant for the implementation in cases as severe and clinically important as suicide or psychosis." (PMID 39598523, 2024).
rheumatoid arthritis (2 papers, 2012 to 2020). A chronic, systemic autoimmune disorder characterized by inflammation in the synovial membranes and articular surfaces. "Diseases with inflammatory processes such as rheumatoid arthritis and gastrointestinal perforation were found to be associated with a reduction of CYP2C19 activity in 47% of the study population." (PMID 32906709, 2020).
schistosomiasis (2 papers, 2021). An infectious disease caused by parasitic trematodes of the genus Schistosoma that colonize human blood vessels and release eggs that can cause granulomatous reactions leading to acute (swimmer's itch or acute schistosomiasis syndrome) or chronic disease. "Since defective variant alleles of both CYP2C9 and CYP2C19 occur at a lower frequency in the black African population, larger sample size studies are needed to explore further the impact of genetic variation on schistosomiasis treatment outcome in the sub-Sharan Africa population." (PMID 34531744, 2021). "We report a significant association of CYP2C19 genotype with plasma PZQ exposure and its metabolic ratio (trans-4-OH-PZQ/PZQ) in schistosomiasis infected children." (PMID 34531744, 2021). "Considering the racemic praziquantel (PZQ), the drug of choice for the treatment of schistosomiasis, the metabolism of (R)-PZQ was mainly catalyzed by CYP1A2 and CYP2C19, whereas the metabolism of (S)-PZQ was mainly by CYP2C19 and CYP3A4." (PMID 34070985, 2021).
serotonin syndrome (2 papers, 2019 to 2023). Serotoninergic syndrome is characterized by an excess of serotonin in the central nervous system, associated with the use of various agents, including selective serotonin reuptake inhibitors (SSRIs). "The results suggest that SSRIs metabolized by CYP2C19 have ADRs significantly associated with gastrointestinal absorption, pain, pregnancy-reproduction, and physiological modulation of the autonomic nervous system including seizures and serotonin syndrome." (PMID 31616600, 2019).
sexual dysfunction (2 papers, 2024). Disturbances in sexual desire and the psychophysiologic changes that characterize the sexual response cycle and cause marked distress and interpersonal difficulty. "Thus, preemptive genotyping of CYP2C19 may help to guide selection of treatment that circumvents selective serotonin reuptake inhibitor-related sexual dysfunction thereby improving outcomes for patients." (PMID 37796764, 2024).
skin cancer (2 papers, 2024). "Our findings support previous work that has shown an increased odds of skin cancer among those treated with voriconazole, and that variation in CYP2C19 impacts this association." (PMID 38819581, 2024). "We conducted a retrospective cohort study to determine how variation in metabolism of voriconazole as measured by metabolizer status of CYP2C19 is associated with the total number of skin cancers a patient develops and the rate of development of the first skin cancer after treatment." (PMID 38699337, 2024).
squamous cell carcinoma (2 papers, 2015 to 2025). A carcinoma arising from squamous epithelial cells. "CYP2C19 PM status interacts significantly with environmental risk factors in modifying susceptibility to squamous cell carcinoma of the head and neck." (PMID 25927305, 2015). "In HNC, CYP2C19 polymorphisms have also been linked to increased cancer susceptibility, with poor-metabolizer alleles (e.g., CYP2C192) showing a significant association with higher risk of developing squamous cell carcinoma." (PMID 40606440, 2025).
steatosis (2 papers, 2021 to 2024). Increased lipid within the cytoplasm of cells. "We found that hepatic CYP2C19 (the human ortholog of Cyp2c29) protein levels were notably reduced in the liver of individuals with NAFLD or NASH compared with those with non‐steatosis livers." (PMID 38303609, 2024).
Stevens-Johnson syndrome (2 papers, 2021 to 2024). Stevens-Johnson syndrome is a limited form of toxic epidermal necrolysis characterized by destruction and detachment of the skin epithelium and mucous membranes involving less than 10% of the body surface area. "CYP2C19*2 (681G>A, rs4244285) and CYP2C19*3 (636G>A, rs4986893) variants were associated with predisposition to Stevens-Johnson syndrome and toxic epidermal necrolysis (SJS/TEN) after CBZ administration and the absence of CYP3A5*3 (rs776746) might be a protective factor." (PMID 33804537, 2021).
21-hydroxylase deficiency (1 paper, 2014). "Gomes and colleagues in 2009 implicated CYP2C19/CYP3A4 in 21-hydroxylation of progesterone in individuals with 21-hydroxylase deficiency thus affecting levels of mineralocorticoids." (PMID 24690327, 2014).
acute graft versus host disease (1 paper, 2019). A syndrome of immunologically mediated tissue damage that may occur following an allogeneic transplant, usually affecting the skin, liver, and GI tract. "Here, we investigated the influence of genotypes of CYP3A5, CYP2C19, and POR on the concentration/dose (C/D) ratio of tacrolimus and episodes of acute graft-versus-host disease (GVHD) in Japanese recipients of allogeneic hematopoietic stem cell transplantation (HSCT)." (PMID 31096684, 2019).
acute myeloid leukemia (1 paper, 2024). Acute myeloid leukemia (AML) is a group of neoplasms arising from precursor cells committed to the myeloid cell-line differentiation. "A study involving prophylactic use of VRC in acute myeloid leukemia patients found that CYP2C19 genotype testing not only avoided prolonging hospital stays but also moderately reduced costs, and it was projected that each patient could save $ 415 in hospitalization expenses." (PMID 38853280, 2024).
allergic rhinitis (1 paper, 2023). Inflammation of the nasal mucous membranes caused by an IgE-mediated response to external allergens. "However, despite continuous PPI therapy, patients with allergic rhinitis and cytochrome P450 2C19 (CYP2C19) rapid metabolizers are at higher risk of developing PPI-resistant EoE." (PMID 37692685, 2023).
alopecia (1 paper, 2025). Hair loss usually from the scalp. "In patients with the CT+TT genotype of the CYP2C19 gene, fatigue severity significantly increased after cycle one, and alopecia severity increased after all chemotherapy cycles compared to baseline (p-value < 0.05)." (PMID 40283974, 2025).
amenorrhea (1 paper, 2025). The absence of menses in a woman who has achieved reproductive age. "Among patients carrying the CC genotype of the CYP2C19 gene, fatigue severity significantly increased after cycles one and two, while amenorrhea and skin toxicity severity significantly increased after cycle one." (PMID 40283974, 2025).
anorexia nervosa (1 paper, 2020). A disorder most often seen in adolescent females characterized by a refusal to maintain a minimally normal body weight, an intense fear of gaining weight, a disturbance in body image, and, in postmenarcheal females, the development of amenorrhea. "In this study, 24 patients with anorexia nervosa at two occasions ingested single oral doses of five test drugs known to be metabolized by CYP1A2, CYP2C9, CYP2C19, CYP2D6, and CYP3A4, respectively." (PMID 32529756, 2020). "Due to the lack of information on the possible effect of low body weight on most CYP enzymes, the aim of this study was to explore whether changes in body weight in patients with anorexia nervosa affect the metabolic activity of the CYP enzymes CYP1A2, CYP2C9, CYP2C19, CYP2D6, and CYP3A4." (PMID 32529756, 2020). "For CYP1A2, CYP2C9, CYP2C19, and CYP2D6, there are no studies on enzyme activities in anorexia nervosa or otherwise underweight subjects." (PMID 32529756, 2020).
Arterial thrombosis (1 paper, 2022). The formation of a blood clot inside an artery. "For instance, serious incidents of arterial thrombosis may develop as a result of therapy failure of clopidogrel, a pro-drug platelet inhibitor, which requires CYP2C19 metabolism to be converted to its active drug metabolite." (PMID 36388934, 2022).
Aspirin-induced asthma (1 paper, 2021). A type of asthma in which aspirin and other nonsteroidal anti-inflammatory drugs (NSAIDs) that inhibit cyclooxygen-ase 1 (COX-1) exacerbate bronchoconstriction. "Preliminary studies have shown the lack of association of Aspirin Induced Asthma and CYP2C19 genotypes, which is not surprising since CYP2C19 is not relevant in aspirin metabolism." (PMID 34621165, 2021).
Ataxia (1 paper, 2023). Ataxia refers to impaired coordination of voluntary muscle movement. "CYP2C19 humanised transgenic mouse is an animal model that can be useful in the research of cerebellar function and ataxia." (PMID 36536486, 2023). "CYP2C19 transgenic mice exhibit abnormal, unilateral ataxia‐like gait, clasping reflex and 5.6‐fold more paw‐slips in the beam‐walking test; the motoric phenotype was more pronounced in youth." (PMID 36536486, 2023). "The initial aim of this study was an in‐depth characterisation of the motoric phenotype seen in CYP2C19 humanised transgenic mice, whereas the subsequent aim was to examine its potential validity as an animal model for cerebellar ataxia." (PMID 36536486, 2023). "Because the validation of new animal models is essential for the understanding of the aetiology and pathophysiology of movement disorders, the objective was to characterise motoric phenotype in CYP2C19 transgenic mice and to investigate its validity as a new animal model of ataxia." (PMID 36536486, 2023). "Even though there is still no obvious link between CYP2C19 and ataxia, unique features of an animal model expressing the human CYP2C19 gene can be a useful addition to the preclinical research of cerebellar function and dysfunction." (PMID 36536486, 2023). "In conclusion, CYP2C19 transgenic mice show a motoric phenotype that shares some, but not all, ataxia‐like features and could be useful in the in vivo investigations of certain aspects of cerebellar function and development." (PMID 36536486, 2023).
cardiac ischemia (1 paper, 2022). "If CYP2C19 activity is reduced due to polymorphism, the protective mechanism against cardiac ischemia is also reduced." (PMID 36843628, 2022).
Cerebellar atrophy (1 paper, 2023). Cerebellar atrophy is defined as a cerebellum with initially normal structures, in a posterior fossa with normal size, which displays enlarged fissures (interfolial spaces) in comparison to the foliae secondary to loss of tissue. "Therefore, it is quite likely that cerebellar atrophy is one of the causes of the observed motoric phenotype in CYP2C19 transgenic mice." (PMID 36536486, 2023).
cerebral atherosclerosis (1 paper, 2024). Atherosclerosis of the cerebral vasculature. "CYP2C19 plays an important role in the metabolism of AA and influences the development of cerebral atherosclerosis by regulating lipid metabolism, blood pressure, and even vascular inflammation." (PMID 39472784, 2024).
Cluster headache (1 paper, 2022). A type of headache characterized by repeated attacks of unilateral pain lasting 15 to 180 minutes and associated with local autonomic signs. "We identified three susceptibility loci, in CAPN2, MERTK, and SATB2, as well as one suggestive locus at CYP2C18/CYP2C19 at genome-wide level in patients with cluster headache in Taiwan." (PMID 36404298, 2022).
Dyskinesia (1 paper, 2019). A movement disorder which consists of effects including diminished voluntary movements and the presence of involuntary movements. "To continue, the results also suggest that CYP2C19 SSRI substrates are significantly associated with coordination and the respiratory system ADRs: dyskinesia, fall, dyspnea, sleep apnoea syndrome." (PMID 31616600, 2019).
hyperuricemia (1 paper, 2021). An abnormally high level of uric acid. "CYP2C9 and CYP2C19 loss-of-function polymorphisms were present to a similar extent in patients without and with hyperuricemia (CYP2C9: 33 (16.4%) vs. 8 (10.4%) patients; CYP2C19: 58 (28.9%) vs. 28 (36.4%) patients; both p > 0.2)." (PMID 32845391, 2021).
Hypoalbuminemia (1 paper, 2025). The concentration of albumin in the blood circulation is below the lower limit of normal. "Previous studies have identified factors influencing voriconazole-related hepatotoxicity, including hypoalbuminemia, voriconazole plasma concentrations, and CYP2C19 genetic polymorphisms." (PMID 41560750, 2025).
Hypomagnesemia (1 paper, 2025). An abnormally decreased magnesium concentration in the blood. "Similar to hypomagnesemia, increased exposure to PPIs with some CYP2C19 phenotypes is the proposed mechanism." (PMID 40070570, 2025). "Hence, it remains unclear whether PPIs-related hypomagnesemia is associated with CYP2C19 genetic predisposition or not." (PMID 40070570, 2025).
inflammatory bowel disease (1 paper, 2024). A spectrum of small and large bowel inflammatory diseases of unknown etiology. "The Inflammatory Bowel Disease (IBD) Panel, which includes NOD2, IL23R, and ATG16L1 genes along with CYP2C19, which are associated with IBD severity and susceptibility can aid in defining genetic risk and tailoring treatment for patients suffering from Crohn’s disease and ulcerative colitis." (PMID 38420192, 2024).
influenza (1 paper, 2024). An acute viral infection of the respiratory tract, occurring in isolated cases, in epidemics, or in pandemics; it is caused by serologically different strains of viruses (influenzaviruses) designated A, B, and C, has a 3-day incubation period, and usually lasts for 3 to 10 days. "The association with influenza remains robust across different subgroups stratified by population characteristics and CYP2C19 phenotypes." (PMID 39012339, 2024). "For the risk of developing influenza, we analyzed the risks among different CYP2C19 metabolizers for the first time, and further observed a significant increase among CYP2C19 normal metabolizers compared to rapid and ultrarapid metabolizers." (PMID 39012339, 2024). "The risks of influenza were significant among CYP2C19 normal metabolizers, and the risk estimate increased among CYP2C19 likely intermediate, intermediate and poor metabolizers, while more information and larger sample sizes on PPI subtypes are still needed to increase the statistical power." (PMID 39012339, 2024).